GAS5 (growth arrest specific 5)
Diseases named in the same sentence as GAS5 in open-access papers (continued):
Sharing a sentence is not in itself a finding about the gene and the disease.
diabetes (continued). "In diabetes, hyperglycemia-induced GAS5 expression shifts polarization from M2 to M1 by upregulating STAT1." (PMID 38473915, 2024). "GAS5 also enhances M1 macrophage polarization, observed in hyperglycemia-induced differentiation in diabetics and in pneumonia-affected children’s macrophages." (PMID 38473915, 2024). "Recently, in an animal model of diabetes, GAS5 was shown to attenuate renal interstitial fibrosis and kidney inflammation by downregulating matrix metalloproteinase-9, a key regulator of ECM remodeling." (PMID 39239549, 2024). "Importantly, our results also showed the ROC analysis indicated that serum lncRNA GAS5 had better diagnostic efficacy in detecting DM patients than DN, suggesting that lncRNA GAS5 may be a good biomarker for predicting the occurrence of diabetes." (PMID 37821982, 2023). "This study aims to investigate the expression of lncRNA GAS5 and miR-21 in T2DM and DN patients to explore their association with diabetes risk factors and markers of kidney injury." (PMID 37821982, 2023). "The application of lncRNA GAS5 and/or miR-21 as biomarkers or intervention targets can provide new insights into the diagnosis and treatment of diabetes." (PMID 37821982, 2023). "In 2015, Carter and colleagues first reported that serum lncRNA GAS5 decreases in patients with type 2 diabetes; the results indicated that individuals with absolute GAS5 < 10 ng/μl have almost twelve times higher odds of having diabetes." (PMID 37821982, 2023). "A recent study showed that GAS5 levels were downregulated in the serum of patients with type 2 diabetes mellitus (T2DM)." (PMID 35178132, 2022). "The aim of this work was to appraise the potential associations of single nucleotide polymorphisms (SNPs) of long non-coding RNA growth arrest-specific 5 (GAS5) with diabetic retinopathy (DR) in a diabetes mellitus (DM) population." (PMID 35456391, 2022). "lncRNA GAS5 expression was increased in peripheral blood mononuclear cells of patients with type 2 diabetes mellitus, and it was positively correlated with aging markers." (PMID 34386495, 2021). "Carter and colleagues (2015) demonstrated that lncRNA GAS5 as a significant indicator of diabetes which can be easily measured in serum in a cohort of US military veterans." (PMID 34284789, 2021). "lncRNA growth arrest-specific 5 (GAS5) and lncRNA ENST00000550337 can serve as a potential diagnostic biomarker for pre-diabetes and T2D mellitus as their increased expression has been reported in diabetic conditions." (PMID 32815547, 2020). "Their receiver operating characteristics curve analysis and quantitative PCR results showed that participants with absolute GAS5 < 10 ng/μL have almost twelve times higher odds of having diabetes." (PMID 31999937, 2020). "One study has reported that the absolute level of serum GAS5 is a good indicator of diabetes, with a value below 10 ng/μL supporting the diagnosis of this disease." (PMID 32413995, 2020). "The ROC analysis revealed an optimal cutoff GAS5 value of ≤10 ng/μL, and individuals with absolute GAS5 <10 ng/μL had significantly greater odds of having diabetes (odds ratio, OR = 11.79 (95% CI: 3.97, 37.26), p < 0.001) than those with higher GAS5 levels." (PMID 28829354, 2017). "Dysregulation of GAS5 expression is frequently observed in various pathologies; for instance, it is often downregulated in many cancer types and exhibits markedly lower serum levels in individuals with diabetes." (PMID 40563948, 2025). "This study showed for the first time the neuroprotective effect of the CE on diabetes induced-brain injury and memory deficit, which could be due to its ability to inhibit pyroptosis via downregulation of lncRNA GAS-5." (PMID 40257540, 2025). "GAS-5 is a lncRNA essential in regulating various diseases, including diabetes." (PMID 40257540, 2025). "As previously stated, GAS5 levels are low in patients with diabetes." (PMID 40331955, 2025).
diabetes (continued). "For instance, increased expression of the lncRNA growth arrest-specific 5 (GAS5) and lncRNA ENST00000550337 has been reported in diabetes condition implying that these molecules can serve as a potential diagnostic biomarker for pre-diabetes and T2DM." (PMID 32182790, 2020). "The lncRNA GAS5 contained in the exosomes is crucial and necessary for the therapeutic potential of hASC exosomes in treating wounds, and, further, GAS5 drives the healing of wounds in an inflammation microenvironment often seen in chronic diseases, such as diabetes and obesity." (PMID 35336800, 2022). "This study showed that GAS5 levels may predict onset of diabetes in adults." (PMID 34284789, 2021). "Growth arrest-specific 5 (GAS-5) is a lncRNA essential for regulating various diseases, including diabetes and cancer." (PMID 40257540, 2025). "At the same time, we verified the role of lncRNA GAS5 and miR-21 in the pathogenesis of T2DM and DN, seeking new therapeutic targets and biomarkers for earlier diagnosis of diabetes and effective treatment of kidney disease." (PMID 37821982, 2023). "The interaction effect test showed that the interaction between urinary GAS5 and hypertension, urinary GAS5 and diabetes was not significant (p = 0.365, 0.629)." (PMID 40685500, 2025). "Elevated lnc‐GAS5 was also correlated with the prevalence of diabetes mellitus in patients with AIS (p = 0.046), but not with other comorbidities." (PMID 34921461, 2022). "Indeed, limiting the degradation of GAS5 by blocking its interaction with up-frameshift mutant (UPF1) increases GAS5 expression and glucose uptake in adipocytes from patients with diabetes." (PMID 35155450, 2021). "Growth arrest-specific 5 (GAS5, ID: 60674) is a novel marker in diabetes mellitus." (PMID 31631065, 2019). "However, the potential role of circulating lncRNAs H19 and GAS5 in type 2 diabetes mellitus (T2DM) and diabetic retinopathy (DR) is not clear." (PMID 31999937, 2020).
non-small cell lung carcinoma (38 papers, 2015 to 2026). A group of at least three distinct histological types of lung cancer, including non-small cell squamous cell carcinoma, adenocarcinoma, and large cell carcinoma. "For instance, GAS5 has been shown to influence macrophage and T-cell infiltration in non-small cell lung cancer and has been implicated as a circulating diagnostic biomarker in plasma of pleural mesothelioma patients." (PMID 39920655, 2025). "For example, in non-small cell lung cancer, GAS5 impedes tumor development by curbing the proliferation of tumor cells." (PMID 41316475, 2025). "The published article titled “Long Noncoding RNA GAS5 Suppresses Tumorigenesis by Inhibiting miR-23a Expression in Non-Small Cell Lung Cancer” has been retracted from Oncology Research, Vol." (PMID 40918461, 2025). "We previously identified that GAS5 inhibited tumor development by suppressing proliferation of tumor cells in non-small cell lung cancer (NSCLC)." (PMID 38762546, 2024). "In this study, the role of the lncRNA GAS5 (growth arrest specific 5) was confirmed in reducing non-small cell lung cancer (NSCLC) cisplatin (DDP) resistance." (PMID 33418541, 2021). "In the same study, it was found that a significant low GAS5 expression in non-small cell lung cancer patients was correlated with poorer prognosis." (PMID 33076450, 2020). "The authors showed that GAS5 competed with PTEN for miR-21 binding, indicating a strong evidence that GAS5/miR-21/PTEN interactions are significant in cis-platin sensitivity in non-small cell lung cancer cells." (PMID 33076450, 2020). "Another recent study confirmed that GAS5 plays a significant role in non-small cell lung cancer, participating in cis-platin resistance." (PMID 33076450, 2020). "Various literatures identify GAS5 as a tumor suppressing lncRNA: for instance, in non-small cell lung cancer, GAS5 is involved in cell proliferation, apoptosis, and migration." (PMID 30733959, 2019). "GAS5 present in exosomes from patients with non-small-cell lung cancer may serve as an ideal serum-based non-invasive marker for identifying early-stage non-small-cell lung cancer." (PMID 38212314, 2024). "Another study led by Qian Tan and collaborators analyzed plasma expression levels of GAS5 from patients with non-small cell lung cancer, and they proposed a combination of GAS5 and CA199 to discriminate early stages of that illness with an area under the curve of 0.734." (PMID 37047453, 2023). "The circulating GAS5 could be used as a novel biomarker for the diagnosis of non-small cell lung cancer." (PMID 29207621, 2017). "For instance, Chuling Li and collaborators, through ROC curve analysis, found that lncRNA GAS5 from exosomes combined with carcinoembryonic antigen could be used to distinguish patients with stage I from other stages of non-small cell lung cancer patients with an AUC of 0.822." (PMID 37047453, 2023). "In non-small cell lung cancer (NSCLC), miR-21 is targeted via the lncRNA GAS5 to increase PTEN expression, with additional support from the lncRNA FER1L4, which inhibits cell proliferation and promotes apoptosis." (PMID 40877546, 2025). "The inhibition of miR-221 via GAS5 sponging has also been demonstrated to upregulate tumor protein p63 (TP63), a central tumor suppressor in non-small cell lung cancer (NSCLC)." (PMID 39941145, 2025). "In non-small cell lung cancer (NSCLC), lncRNA growth arrest-specific 5 (GAS5) inhibits miR-135b-5p and enhances radiosensitivity." (PMID 35685474, 2022). "Hyperglycemia inhibits the expression of growth arrest-specific 5 (GAS5) and subsequently elevates tribbles homolog 3 (TRIBS3), which inhibits apoptosis and induces proliferation of non-small cell lung cancer." (PMID 31546918, 2019).
non-small cell lung carcinoma (continued). "Treatment of non-small cell lung cancer (NSCLC) cell lines A549, H1299 and H1975 with ailanthone, a compound derived from Ailanthus altissima (commonly known as the tree of heaven), which inhibits UPF1 translation, impedes NMD and stabilises GAS5." (PMID 40944360, 2025). "Furthermore, the GAS5/miR-21/PTEN axis influences cisplatin resistance and chemosensitivity, in cervical cancer and non-small cell lung cancer (NSCLC), respectively." (PMID 29702599, 2018). "Likewise, GAS5 levels in plasma are found to be decreased in diabetes type 2 patients and are even further decreased in CAD patients, but GAS5 levels in plasma are also decreased in non-small cell lung cancer patients." (PMID 30893946, 2019). "Additionally, a study revealed that compared with adjacent noncancerous tissues, Gas5 expression was diminished in non-small cell lung cancer tissues, which was highly related to TNM staging and tumor size." (PMID 29308053, 2018).
pancreatic cancer (35 papers, 2015 to 2025). "GAS5 is a lncRNA in which high expression causes pancreatic cancer cells to enter a quiescent state and when expression decreases, cells re-enter a cycling state." (PMID 37464317, 2023). "The expression of MEG3 has been shown to be negatively correlated with tumor metastasis and vascular invasion in pancreatic cancer Similarly, lncRNA Gas5 was found to inhibit metastasis of pancreatic cancer by regulating the miR-32-5p/PTEN pathway." (PMID 36874093, 2023). "In pancreatic cancer, the lncRNA GAS5 regulates quiescence in cancer stem cells, which by extension, affects tumor recurrence." (PMID 37464317, 2023). "For example, in pancreatic cancer, GAS5 functions as a competing endogenous RNA for miR-221 to suppress cell growth, metastasis, and gemcitabine resistance by mediating epithelial-mesenchymal transformation (EMT) and tumor stem cell self-renewal." (PMID 36106122, 2022). "In pancreatic cancer, downregulation of GAS5 increased cell proliferation by regulating CDK6 transcriptionally, suggesting the tumor suppressive role of GAS5." (PMID 34439315, 2021). "GAS5 which is down-regulated in many cancers likes CRC, NSCLC, breast, and pancreatic cancer indicates the over-expression of GAS5 aids in regression of the tumour." (PMID 34303380, 2021). "lncRNA growth arrest-specific 5 (GAS5) is a tumor suppressor found in various cancers including pancreatic cancer." (PMID 34439315, 2021). "It has been reported that lncRNA GAS5 regulates the Hippo signaling pathway through repressing miR-181c-5p and antagonizes the chemoresistance of pancreatic cancer cells." (PMID 34037089, 2021). "Studies also showed that GAS5 suppressed pancreatic cancer metastasis and chemoresistance through epigenetic regulation of miR-32 or miR-181c." (PMID 34439315, 2021). "On the other hand, the lncRNA GAS5 has been found to suppress metastasis of pancreatic cancer via the regulation of the miR-32-5p/PTEN axis." (PMID 34827663, 2021). "In pancreatic cancer cells, GAS5 regulates chemoresistance to gemcitabine and metastatic ability of transformed cells." (PMID 34368145, 2021). "As previously discussed, the lncRNA GAS5 also targets miRNA-221 and can reduce its levels in pancreatic cancer cells resulting in increased sensitivity to gemcitabine via relief of suppression of the miRNA-221 target SOCS3." (PMID 31979312, 2020). "The levels of GAS5 are significantly decreased in pancreatic cancer tissues compared with normal control." (PMID 33195407, 2020). "In vitro, GAS5 was found to inhibit the viability, migration, and invasion of pancreatic cancer cells." (PMID 30606744, 2019). "To see if in CD133+ pancreatic cancer cells Sox2 regulated GAS5 mediated growth arrest, we next silenced Sox2 (with siRNA) and studied the expression of GAS5 in CD133Hi cells." (PMID 31740660, 2019). "In pancreatic cancer the expression level of GAS5 has been verified to be obviously reduced in pancreatic cancer tissues, and GAS5 upregulation represses cell proliferation by suppressing expression of cyclin-dependent kinase 6 (CDK6) in vitro and in vivo." (PMID 31182630, 2019). "Analysis of public database like Oncomine for GAS5 expression in pancreatic cancer showed that GAS5 was overexpressed in pancreatic tumors when compared to the normal tissues." (PMID 31740660, 2019). "To visualize GAS5 in the pancreatic tumors, we next performed a fluorescent in situ hybridization with GAS5 on pancreatic cancer patient tumor slides as well as on implanted tumors with MIA-CD133Hi cells." (PMID 31740660, 2019). "A previous study identified the crucial role for GAS5 in the molecular etiology of pancreatic cancer and as a potential therapy target." (PMID 27992375, 2017). "In this study, we confirmed the existence of GAS5/miR-32-5p/PTEN signaling pathway in pancreatic cancer cell metastasis." (PMID 29225772, 2017).
pancreatic cancer (continued). "Moreover, GAS5 was shown to inhibit pancreatic cancer cell proliferation by inhibiting the transcriptional activity of glucocorticoid receptor (GR) in CD133+ population which is often attributed to tumor metastasis and recurrence." (PMID 34094978, 2021). "Expression of GAS5 has been shown to be downregulated in a variety of cancers, such as lung, breast, bladder, gastric, prostate, and pancreatic cancer, suggesting that GAS5 may play a tumor suppressor role during cancer progression." (PMID 34440661, 2021). "LncRNA GAS5 modulates miR‐32‐5p/PTEN axis to suppress pancreatic cancer metastasis." (PMID 33448691, 2020). "Additionally, GAS5 overexpression was more common in the pancreatic ductal adenocarcinoma and compared to the other types of pancreatic cancers." (PMID 31740660, 2019). "Our results confirmed that GAS5 was indeed overexpressed in pancreatic cancer." (PMID 31740660, 2019). "The precise role of GAS5 in pancreatic cancer (PC) progression is currently unknown, so the aim of this study was to explore the functional participation of GAS5 in PC metastasis." (PMID 29225772, 2017). "For instance, by inhibiting the expression of miR-103 and miR-32-5p, GAS5 induces the PTEN/PI3K/AKT pathway, thereby suppressing the tumor progression of endometrial cancer and pancreatic cancer cells." (PMID 39941145, 2025). "The GAS5/miR-221/SOCS3 cascade has been identified as an important modulator of EMT and CSC function in pancreatic cancer." (PMID 34368145, 2021). "GAS5 also reversed EMT, inhibited metastasis and increased the sensitivity of pancreatic cancer stem cells to gemcitabine through targeting miR-221/SOCS3 signaling." (PMID 34439315, 2021). "LINC01111/miR-3924, LINC01963/miR-641, DGCR5/miR-27a-3p, GAS5/miR-32-5p, and LINC00261/miR-23a-3p axes are examples of the latter type of lncRNA/miRNA interactions in the context of pancreatic cancer." (PMID 34827663, 2021). "It was shown in in vivo and in vitro experiments of a previous study, upregulated GAS5 promoted the expression of SOCS3, thus inhibiting the growth, metastasis, and Gem resistance of pancreatic cancer." (PMID 34868904, 2021). "To study if GAS5 was upregulated in pancreatic cancer cells under chemotherapy induced stress, we treated KPC001 cells with 100 nM Gemcitabine for 7 days and analyzed the GAS5 and CD133 expression." (PMID 31740660, 2019). "This indicates that miR-32-5p negatively regulates the expression of PTEN and mediates the effect of GAS5 on the expression of PTEN, which in turn affects pancreatic cancer proliferation." (PMID 30606744, 2019). "At the same time, several lncRNAs (e.g., linc-ROR, GAS5 and linc-DYNC2H1-4) have been identified as ceRNAs to confer drug resistance in pancreatic cancer." (PMID 31514732, 2019). "Our study shows that in pancreatic cancer, CD133+ cells have a high expression of GAS5, which is regulated by the self-renewal transcription factor Sox2." (PMID 31740660, 2019). "Recent studies have demonstrated that certain lncRNAs can act as competing endogenous RNA (ceRNAs) or miRNA “sponges” to modulate chemotherapy sensitivity in pancreatic cancer, such as linc-ROR, GAS5 and linc-DYNC2H1-4." (PMID 31514732, 2019). "Our study thus showed that GAS5 acts as a molecular switch for regulating quiescence and growth arrest in CD133+ population, that is responsible for aggressive biology of pancreatic tumors." (PMID 31740660, 2019). "Our study thus showed that GAS5 acts as a molecular rheostat for regulating quiescence and growth arrest in CD133+ population, that is responsible for aggressive biology of pancreatic tumors." (PMID 31740660, 2019). "Several recent studies have documented the essential role of GAS5 as a “molecular switch” to control quiescence/stemness in CSCs, including the CD133 + CSCs in pancreatic cancer and HCT116-derived CSCs, as well as for self-renewal and pluripotency of mouse embryonic stem cells." (PMID 34885174, 2021).
pancreatic cancer (continued). "Interestingly, when pancreatic cancer cell line MIA-PACA2 was cultured under hypoxia or nutritional stress, GAS5 expression was also increased." (PMID 31740660, 2019). "GAS5 silencing increases—and ectopic GAS5 lncRNA expression decreases—CDK6 mRNA and protein levels in cell lines; a similar, inverse relationship between GAS5 and CDK6 levels has been reported in bladder and pancreatic cancer tissues, suggesting that this interaction is operative in vivo." (PMID 26198250, 2015).